CRP (C-reactive protein)
Diseases named in the same sentence as CRP in open-access papers (continued):
Sharing a sentence is not in itself a finding about the gene and the disease.
leukocytosis (continued). "Laboratory results showed leukocytosis (16,200/mm3), anemia (Hb 9.8 g/dL), and elevated CRP (110 mg/L)." (PMID 41341186, 2025). "Elevated CRP (>10 mg/L) was present in 62 patients (89.86%) on admission, while leukocytosis was observed in 16 patients (23.2%)." (PMID 41556000, 2025). "Laboratory findings showed leukocytosis (>9.5 × 109/L) in 21 patients (84.0%), increased absolute neutrophil counts (>6.3 × 109/L) in 22 (88.0%), and elevated CRP levels in 23 (92.0%)." (PMID 40909246, 2025). "Laboratory findings at initial presentation demonstrated leukocytosis with neutrophilia and eosinophilia, mild elevation of alanine aminotransferase, hypoalbuminemia, and markedly raised inflammatory markers (CRP and procalcitonin)." (PMID 41523566, 2025). "Laboratory findings revealed leukocytosis, neutrophilia, and an elevated C-reactive protein (CRP) level." (PMID 40699359, 2025). "Laboratory values at the time of admission showing anemia (low hemoglobin, hematocrit, and red blood cell count), leukocytosis with neutrophilia, elevated inflammatory markers (CRP), and mild metabolic acidosis." (PMID 41393628, 2025). "In our study, we observed hyperlipasemia in 100% of cases, leukocytosis with neutrophil predominance in 78.5% of patients, and elevated CRP in 100% of cases." (PMID 40955254, 2025). "On day 10, a nosocomial infection was suspected due to persistent fever (39°C), leukocytosis at 25,340/mm3, and a CRP level of 281 mg/L." (PMID 40364883, 2025). "The presence of inflammatory markers raised ESR, CRP, and leukocytosis) and positive autoimmune markers (ANA) Golgi-type (AC-22* +) suggesting increased risk of ischemia." (PMID 40416235, 2025). "Approximately half of all cases present with leukocytosis, and systemic inflammatory markers—such as C-reactive protein (CRP) and erythrocyte sedimentation rate (ESR)—are commonly elevated." (PMID 41333773, 2025). "Laboratory examinations showed leukocytosis (11,920 counts/μL [normal: ≤9,000 counts/μL]), thrombocytopenia (8.1×104/μL [normal: 15-35×104/μL]), and elevated liver enzymes and C-reactive protein (10.45 mg/dL [normal: <0.5 mg/dL])." (PMID 41246602, 2025). "The results highlight leukocytosis with elevated neutrophils and eosinophils, as well as an increased C-reactive protein level." (PMID 40922885, 2025). "Laboratory investigations showed a slightly elevated C-reactive protein (CRP) level with leukocytosis at 19,540/mm3, predominantly lymphocytic (13,000/mm3)." (PMID 40861603, 2025). "The very high leukocytosis and markedly raised CRP in this patient indicated a strong systemic inflammatory response." (PMID 41541145, 2025). "Laboratory markers showed leukocytosis (20 × 109/L) and markedly elevated C-reactive protein (CRP, 320 mg/L)." (PMID 40699733, 2025). "The lab workup showed leukocytosis, high C-reactive protein (CRP) levels, and an increased erythrocyte sedimentation rate (ESR)." (PMID 40026992, 2025). "The patients with HSV and adenovirus infections tended to have leukocytosis, neutrophilia, and high CRP, making differentiation from bacterial infection difficult." (PMID 40142520, 2025). "On laboratory assessment, leukocytosis (>11,000/cmm) was present in 19 patients (63.3%), elevated CRP in 18 of 28 tested patients (60.0%), and abnormal liver function tests in 14 patients (46.6%)." (PMID 41018368, 2025). "The differences between the groups were the expected increase in inflammatory markers (leukocytosis and elevated C-reactive protein) in the UTI group (P < 0.001), and the different antibiotic treatment prescribed after admission." (PMID 39607509, 2025). "In the placebo group, increased C-reactive protein levels, leukocytosis, and back pain were reported in one patient each." (PMID 40135237, 2025). "Laboratory blood tests displayed leukocytosis [16.42 (3.4–9.7*109/L)] with neutrophil predomination [12.78 (2.06–6.49 × 109/L)] and elevated CRP levels [94.3 (<5 mg/L)]." (PMID 40710859, 2025).
leukocytosis (continued). "Chest X-ray (CXR) revealed an enlarged cardiac silhouette, and laboratory investigations showed leukocytosis (23,900/μL) and an elevated C-reactive protein (CRP 15.86 mg/dL)." (PMID 41286644, 2025). "In the emergency department, laboratory workup showed elevated inflammatory markers, including leukocytosis and elevated CRP levels." (PMID 41399589, 2025). "Initial laboratory tests revealed leukocytosis (12.4 × 109/L) and elevated C-reactive protein (CRP) (8.6 mg/dL), while renal and hepatic function tests were within the reference range." (PMID 41327134, 2025). "Our findings corroborate this pattern: on admission, 43.8% of patients had leukocytosis, 56.3% had anaemia, 41.7% showed elevated CRP and 60.0% had raised ESR, whereas conventional tumour markers remained within normal limits." (PMID 40980125, 2025). "Laboratory findings often show increased inflammation indices such as leukocytosis and elevated C-reactive protein (CRP) and procalcitonin." (PMID 40265142, 2025). "The only three published cases involved native joint septic arthritis, observed in patients with sickle cell disease, all presenting with elevated CRP, leukocytosis, and confirmed by MRI and C. difficile isolation from blood or/and joint fluid." (PMID 40723972, 2025). "In one study, 80% of anti-IFN-γ AAb-positive patients with opportunistic infections presented with peripheral lymphadenopathy, leukocytosis, lymphopenia, and elevated C-reactive protein (CRP)." (PMID 40711078, 2025). "Blood tests showed neutrophil-dominant leukocytosis, elevated liver enzymes, moderate anemia, hyperferritinemia, and increased C-reactive protein (CRP) and erythrocyte sedimentation rate (ESR) levels." (PMID 40065895, 2025). "Initial blood investigations revealed leukocytosis, with a white cell count of 17.6 × 109/L and elevated serum C-reactive protein (CRP) of 202 mg/L." (PMID 41487790, 2025). "Laboratory studies revealed leukocytosis peaking at 25.06 × 109/L with neutrophil predominance, procalcitonin exceeding 100 ng/mL, and markedly elevated C-reactive protein." (PMID 41426715, 2025). "Laboratory tests typically show signs of systemic inflammation, such as leukocytosis and elevated inflammatory markers, including C-reactive protein (CRP)." (PMID 41440529, 2025). "Blood tests showed leukocytosis (20810/μL) and elevated C-reactive protein levels (8.1 mg/dL), while hemoglobin levels (14.1 g/dL) were normal." (PMID 40012964, 2025). "Laboratory testing showed leukocytosis (26.08 × 109/L), mild anemia (hemoglobin 10.9 g/dL), thrombocytopenia (81 × 109/L), elevated lactate dehydrogenase (458 U/L), and C-reactive protein (49 mg/L)." (PMID 41020826, 2025). "Upon admission for RAIT, laboratory evaluation revealed mild leukocytosis with neutrophilia, along with elevated liver enzymes, lactate, and C-reactive protein levels." (PMID 41472144, 2025). "Hematological tests revealed leukocytosis (20.9 × 109/L), while biochemical tests showed elevated C-reactive protein (CRP) levels (22.4 mg/L)." (PMID 40136596, 2025). "Laboratory findings showed significantly elevated high-sensitivity troponin I levels (6.3 mg/L), leukocytosis (12,400/mm3) with eosinophilia (10.2%), and mildly elevated C-reactive protein (6.4 mg/L), indicative of systemic inflammation." (PMID 39941439, 2025). "Laboratory evaluation revealed mild leukocytosis (11.63 × 103/μL) with normal C-reactive protein levels and liver function tests." (PMID 40692726, 2025). "Ceftriaxone was administered to address the leukocytosis and elevated C-reactive protein (CRP) levels." (PMID 40283192, 2025). "Laboratory investigations revealed leukocytosis, markedly elevated C-reactive protein, hyponatremia, and renal impairment, while blood cultures were negative after 48 hours of incubation." (PMID 41328147, 2025). "The Appendicitis Inflammatory Response (AIR) score and other similar algorithms primarily rely on clinical symptoms, leukocytosis, and CRP." (PMID 41185821, 2025).
leukocytosis (continued). "Infectious fever is initiated by microbial pyrogens that elevate the hypothalamic set point via prostaglandin-mediated pathways, often accompanied by leukocytosis, elevated C-reactive protein (CRP), and positive amniotic fluid cultures." (PMID 41040641, 2025). "The initial investigation revealed localized RLQ pain and leukocytosis, along with elevated C-reactive protein (CRP)." (PMID 40951094, 2025). "Initial laboratory investigations revealed leukocytosis, neutrophilia, and elevated C-reactive protein (CRP) and procalcitonin, suggestive of systemic inflammation, potentially indicating torsion/infarction." (PMID 40951031, 2025). "Patients with HSV, adenovirus, and enterovirus infection had higher rates of leukocytosis and neutrophilia and high CRP, resembling acute bacterial infections." (PMID 40142520, 2025). "On blood examination, significant leukocytosis and elevated C-reactive protein (CRP) (169 mg/L; RI, 0–9 mg/L) were noted." (PMID 40134764, 2025). "The Appendicitis Inflammatory Response (AIR) score includes leukocytosis, neutrophilia, and CRP, and has been shown to be useful in diagnosing appendicitis." (PMID 41473919, 2025). "Abnormal parameters, including leukocytosis, neutrophilia, lymphopenia, eosinopenia, high CRP, and d-dimer, were found to be significantly different between the groups." (PMID 40733571, 2025). "Laboratory tests showed leukocytosis, elevated C-reactive protein, renal impairment, and hyponatremia." (PMID 40322434, 2025). "Laboratory studies were significant for leukocytosis, elevated C-reactive protein (CRP), and erythrocyte sedimentation rate (ESR)." (PMID 40065897, 2025). "Initial laboratory investigations revealed leukocytosis and elevated C-reactive protein, while renal function parameters remained within normal limits." (PMID 40922879, 2025). "The characteristic findings included livedo reticularis, blue toe syndrome, leukocytosis (21,190/μL), elevated C-reactive protein (11.4 mg/dL), and acute kidney injury (creatinine 3.81 mg/dL)." (PMID 41010716, 2025). "Laboratory testing was significant for an elevated AST, ALT, total bilirubin, conjugated bilirubin, GGT, C-reactive protein (CRP), and increased leukocytosis and thrombocytosis." (PMID 41179046, 2025). "Physical examination revealed a tympanic temperature of 38.9oC, leukocytosis with neutrophilia, and elevated C-reactive protein levels." (PMID 40255710, 2025). "Inflammatory markers, such as leukocytosis, C-reactive protein (CRP), and gene expression of IL-17A and IL-6, were positively correlated with these MS-associated species." (PMID 40282300, 2025). "Blood tests showed leukocytosis with neutrophilic predominance, anemia, thrombocytosis, elevated hepatobiliary enzymes, increased C-reactive protein (CRP; 22.35 mg/dL), and hypoalbuminemia." (PMID 41141125, 2025). "Laboratory testing on admission showed leukocytosis with neutrophilia, thrombocytosis, elevated C-reactive protein (CRP) and procalcitonin, with mild decreases in albumin and sodium; total bilirubin and alanine aminotransferase were within reference ranges." (PMID 41341343, 2025). "Laboratory tests revealed leukocytosis (30 ×103/μL), neutrophilia (94.8%), and an elevated C-reactive protein (CRP) level of 159 mg/L." (PMID 40130256, 2025). "Hematological investigations were significant for leukocytosis, mild anemia, elevated C-reactive protein (CRP), high erythrocyte sedimentation rate (ESR), and elevated serum creatinine." (PMID 39897324, 2025). "Laboratory investigations showed a leukocytosis of 17,200/μL with a left shift and a mildly elevated C-reactive protein (CRP) level of 1.68 mg/dL." (PMID 41476856, 2025). "Laboratory tests revealed significant leukocytosis and a markedly elevated C-reactive protein level (247.5 mg/L)." (PMID 41153265, 2025). "Laboratory evaluation showed leukocytosis (24.2 × 109/L) with neutrophil predominance (17.4 × 109/L) and markedly elevated C-reactive protein (CRP) at 237 mg/L." (PMID 41020018, 2025).
leukocytosis (continued). "Laboratory tests showed a leukocytosis of 13,600/μL with 10,200 neutrophils/μL and a C-reactive protein (CRP) of 115 mg/L." (PMID 39912010, 2025). "During these events, there was leukocytosis, and raised inflammatory markers, such as c-reactive protein, were observed." (PMID 39941428, 2025). "Initial laboratory investigations demonstrated leukocytosis, thrombocytopenia, hyponatremia, normal anion gap metabolic acidosis, transaminitis, and elevated C-reactive protein (CRP)." (PMID 41210057, 2025). "The transient fever, mild leukocytosis, and elevated CRP likely resulted from the acute inflammatory process associated with the torsion." (PMID 40347907, 2025). "Findings included marked leukocytosis with neutrophilia, elevated CRP (C-reactive protein), severe renal impairment with reduced eGFR (estimated glomerular filtration rate), and electrolyte disturbance (hyponatraemia)." (PMID 41018413, 2025). "Routine laboratory markers such as leukocytosis and C-reactive protein (CRP) are widely used to support diagnosis of appendicitis, but they lack specificity in differentiating uncomplicated from complicated disease." (PMID 41230472, 2025). "For example, the simultaneous presence of elevated CRP, leukocytosis, and neutrophilia increases sensitivity to nearly 97-100%, but the predictive value of each marker individually is low." (PMID 41141184, 2025). "Common findings include anemia, leukocytosis, neutrophilia, lymphopenia, and elevated inflammatory markers such as ferritin, CRP, and D-dimers, indicating ongoing inflammation and coagulation disturbances." (PMID 41227273, 2025). "Laboratory tests revealed significant leukocytosis with neutrophilia, and inflammatory markers, including C-reactive protein and erythrocyte sedimentation rate, were elevated." (PMID 40026964, 2025). "Laboratory tests showed marked leukocytosis and elevated C-reactive protein (CRP), and imaging confirmed tenosynovitis with abscess formation involving the extensor compartment." (PMID 41399589, 2025). "Blood tests showed mild leukocytosis (9,600/μL), elevated CRP (1.27 mg/dL), and hyperammonemia consistent with worsening hepatic dysfunction." (PMID 41450394, 2025). "The patient presented with leukocytosis, elevated inflammatory markers (C-reactive protein (CRP)), electrolyte imbalances, and a borderline elevated lactate level, suggestive of early tissue hypoperfusion." (PMID 41362556, 2025). "Bloodwork was notable for mild leukocytosis, along with elevated C-reactive protein (CRP) and erythrocyte sedimentation rate (ESR)." (PMID 40755582, 2025). "In the control group, most laboratory parameters remained within the normal range; only 2 cases (11.1%) each showed leukocytosis and thrombocytosis, 9 (50.0%) had elevated CRP, and 1 (5.6%) showed elevated D-dimer." (PMID 41356465, 2025). "Peripheral blood tests revealed leukocytosis (21.54 × 103/μL) and a mild elevation of C-reactive protein (CRP), and a magnetic resonance imaging (MRI) of the head showed empty sella." (PMID 41497944, 2025). "Cefotaxime was added due to worsening of the patient’s condition, leukocytosis, and rising CRP, which was stopped after three days when blood culture results showed no growth after 48 hours of incubation." (PMID 40161139, 2025). "Initial evaluation revealed severe anemia, marked leukocytosis, and a significantly elevated C-reactive protein level." (PMID 41552247, 2025). "Laboratory testsrevealed normocytic and normochromic anemia, leukocytosis with a left shift,elevated C-reactive protein (CRP), and hypoalbuminemia." (PMID 41404348, 2025). "Laboratory findings that support the diagnosis of AOSD include leukocytosis (especially neutrophils), anemia, elevated ferritin, CRP, ESR, and abnormal liver function tests (AST and ALT)." (PMID 40110271, 2025).
leukocytosis (continued). "Laboratory tests in the emergency department revealed AKI with leukocytosis and markedly elevated inflammatory markers (C-reactive protein (CRP) 111 mg/L, procalcitonin 81 ng/mL), leading to her admission to the nephrology department." (PMID 41179021, 2025). "Immediately before the operation, mild leukocytosis and neutrophilia were recorded (12.55 × 109/L and 10.75 × 109/L, respectively), with elevated values of CRP, fibrinogen, D‐dimer, PT, and aPTT (69.8 mg/L, 6.3 g/L, 1.3 mg/L, 13.8 s, and 39.7 s respectively)." (PMID 40534446, 2025). "Laboratory tests revealed leukocytosis, an increased level of CRP, transaminases and total/direct bilirubin." (PMID 40611140, 2025). "Upon admission, laboratory findings included leukocytosis with neutrophilia and an elevated C-reactive protein (CRP) level of 16.83 mg/dL, despite the absence of pyuria." (PMID 41146779, 2025). "Although CRP and leukocytosis are widely used as inflammatory markers, their specificity is limited." (PMID 40462780, 2025). "The following day, she experienced another febrile episode with leukocytosis (10.43 × 109/L) and elevated CRP (185.2 mg/L)." (PMID 41440229, 2025). "Intracranial complications are often associated with leukocytosis, elevated ESR, and raised CRP levels, indicative of the bacterial origin of the complication." (PMID 39518567, 2024). "Laboratory tests revealed elevated inflammatory markers, namely, leukocytosis and neutrophilia, with a leukocyte count of 18,000/μL, neutrophils at 88%, and C-reactive protein (CRP) at 18.3 mg/dL." (PMID 39723325, 2024). "Due to regional lymph node involvement, leukocytosis and elevated CRP can be detected, especially in the early stages of the infection." (PMID 39061683, 2024). "His laboratory analysis revealed leukocytosis, bandemia (an increased number of immature white blood cells), and an elevated C-reactive protein (CRP) level." (PMID 39619414, 2024). "Leukocytosis and elevated C-reactive protein (CRP) levels were common in patients receiving ECMO irrespective of the infection state in the peri-decannulation period." (PMID 39797141, 2024). "In patients with pyelonephritis, leukocytosis, C-reactive protein (CRP), and procalcitonin (PCT) are the most commonly used biomarkers for diagnosis and treatment monitoring." (PMID 38611690, 2024). "Laboratory tests revealed microcytic hypochromic anemia, leukocytosis, eosinophilia, and thrombocytosis with elevated C-reactive protein (CRP) and erythrocyte sedimentation rate (ESR)." (PMID 39867099, 2024). "Routine investigations showed mild leukocytosis, normocytic hypochromic anemia, and mildly elevated C-reactive protein (CRP)." (PMID 39050352, 2024). "The adverse effects of leukocytosis, elevated CRP levels, and other inflammatory markers, such as IL-6, on a prognosis following stroke have been well-documented in the general stroke population, and in patients after MT in particular." (PMID 38565588, 2024). "Laboratory investigations showed leukocytosis of 18,5 x 109/L and elevated C-reactive protein (CRP) to 15.2 mg/dl." (PMID 39429379, 2024). "Laboratory tests showed Hb 14.2 g/dL, leukocytosis (24,200/μL), creatinine 1 mg/dL, C-reactive protein 20.77 mg/dL, and lactate 0.6 mmol/L." (PMID 39687832, 2024). "A report of 100 cases of EN indicated that leukocytosis and CRP elevation are generally milder in EN than in SS." (PMID 39310601, 2024). "Laboratory findings in RDD patients include leukocytosis; neutrophilia; normocytic anemia; thrombocytosis; elevated CRP, ESR, and ferritin levels; and hypergammaglobulinemia." (PMID 38907282, 2024). "In acute pericarditis patients, leukocytosis was observed in 13 (37%) patients, whereas high C-reactive protein and high erythrocyte sedimentation rates were present in 29 (83%) and 12 (34%), respectively." (PMID 39728899, 2024).